FN1 (fibronectin 1)
Diseases named in the same sentence as FN1 in open-access papers (continued):
Sharing a sentence is not in itself a finding about the gene and the disease.
cancer (continued). "Next, the expression profiles of CD44, FGF2, FGF10, KDM6A, FN1, and MMP2 were evaluated using the OcoDB database across different clinical stages, age groups, and racial categories in cancer patients." (PMID 39833941, 2025). "Fn1 was enriched in ‘ECM-receptor interaction’, ‘Pathways in cancer’, ‘Focal adhesion’, ‘AGE-RAGE SP in diabetic complications’, ‘Proteoglycans in cancer’, and ‘PI3K-Akt signaling pathway’." (PMID 40497967, 2025). "FN1, a crucial component of extracellular matrix (ECM) organization, plays a pivotal role in cancer progression and metastasis." (PMID 40564071, 2025). "The FN1 fibrillar not only provides binding sites for other ECM components, such as collagen, but also for cancer cells and other growth factors, particularly TGF-β, which initiates epithelial-mesenchymal transition." (PMID 41405822, 2025). "Ligand–receptor interaction networks quantified through the CellChat system demonstrated that cancer zone A was characterized by COLLAGEN, FN1, and ANGPTL signaling pathways." (PMID 40723284, 2025). "Cancer cells are defined as cells expressing high MKI67, CAV1, and CTNNB1 and present spatial variations in the expression of VEGFC, FN1, and NRP1." (PMID 40081369, 2025). "Among these, collagen family genes and FN1 highly expressed in CAFs interact with the CD44 receptor on immune cells, driving cancer progression." (PMID 40333631, 2025). "Firstly, single-cell sequencing identified the specific high expression of FN1 in metastatic CAF subsets, which directly drives EMT and cancer cell invasion via activation of the PI3K/AKT signaling pathway through integrin receptors." (PMID 40678072, 2025). "TGF-β was commonly expressed by multiple cell types, including cancer cells, stromal cells and BECs, and its expression was upregulated in metastatic LNs, potentially driving the expression of MGP, FN1, SOX4, PDPN, and HEY1 in LECs." (PMID 41249124, 2025). "The PI3K-Akt signaling and proteoglycans in cancer were significantly enriched, involving proteins such as COL1A1, FN1, THBS1, FLNA, and ACTB." (PMID 40710368, 2025). "We thoroughly investigated the biological significance of EDN1/ARRB1 expression with COL1A1 or FN1 by examining their expression levels and predictive value for OS or PFS and SOC cancer staging (stages 1 + 2 or 3 + 4)." (PMID 39985042, 2025). "CAFs produce an FN1-rich ECM with anisotropic fiber orientation, which guides cancer cells to migrate directionally." (PMID 38892190, 2024). "Among all of these, MMP2, MMP9, FN1, CD44, SERPINE1, and CAV1 are the most famous collaborators with PLAUR in the cell migration of multiple cancer types." (PMID 38396677, 2024). "In addition, EMT is a crucial step of cancer cell migration and invasion, we focused on the possible associations between P4HA3 expression and classic EMT markers, such as Vimentin (VIM), TWIST1, Snail2 (SNAL2), Snail1 (SNAL1), Fibronectin1 (FN1), and N-cadherin (CDH2)." (PMID 39504328, 2024). "FN1 and MSN are aberrantly expressed in cancer cells and play a role in maintaining their epithelial character." (PMID 38421619, 2024). "The uniform dysregulation of FN1, F5, and THBS1 across all cancer stages highlights these genes as possible biomarkers and their potential utility in cancer diagnosis and prognosis." (PMID 39456895, 2024). "We provide evidence for a novel mechanism in which THUMPD3 affects the alternative splicing of cancer relevant and ECM enriched mRNAs, such as Fibronectin-1 mRNA, thereby promoting a molecular environment permissive to lung cancer progression." (PMID 39656728, 2024). "Two proteins included in the carcinoma EV signature were the ECM proteins biglycan (BGN) and fibronectin (FN1), which were among the most over-represented ECM-related proteins in EV isolates from all carcinoma cell lines." (PMID 39462388, 2024).
cancer (continued). "Numerous recent studies consistently indicate that activated fibroblasts exert control over the progression and metastasis of cancer through their active secretory protein, comprising MMP11, MMP14, and FN1." (PMID 38057779, 2023). "RNAPII occupancy also mirrored that of NELF-E binding, as exemplified by cancer stem cell marker CD44 and mesenchymal gene FN1, both of which are upregulated upon Dox induction in control cells but curtailed in NELF-E KD cells." (PMID 37117180, 2023). "Further analysis of cellular communication between all CAFs and cancer cells in the cSCC TME revealed that collagen-related and Fibronectin 1 (FN1) signaling pathway networks are particularly active." (PMID 37669956, 2023). "Integration events occurring in single samples were observed in the following cancer-driver genes: TERT, KMT2B (MLL4), RIMS1, FN1, RBFOX1, CNTNAP2 and THRB7,11,12,14,27,28." (PMID 37400627, 2023). "Some other proteins of interest include the surface protein FN1 and the enzyme butyrylcholinesterase (BCHE), both being known as unfavorable prognostic markers for different cancers along with EphA2." (PMID 37637064, 2023). "This study also investigated the signaling pathways involved in COL10A1/FAP/FN1, and the results showed that FN1 is a component of the extracellular matrix (ECM), which is a characteristic gene for cancer." (PMID 38063927, 2023). "We identified distinct genes including KLK4, FN1, PBOV1, TPM2, and FLNA which are known to be involved in PCa pathways along with IGF1, TPD52, and SRSF1 that are involved in different cancer pathways." (PMID 37218885, 2023). "Analysis of the CRC dataset from the cancer genome atlas (TCGA) demonstrated a positive correlation between THBS1 and mesenchyme-related genes (VIM and FN1) and pan-myeloid markers (CD14 and CD33)." (PMID 37749092, 2023). "Remarkably, some receptors (ERBB2, ITGA3, and ITGB6) were mainly expressed in cancer cells, and their putative ligands (NRG1 and FN1) were over-expressed in CAFs." (PMID 37879219, 2023). "FN1 is one of the most crucial components of the extracellular matrix (ECM), involved in the regulation of cancer progression." (PMID 37563650, 2023). "The results of immunohistochemistry assays proved that COX-2 overexpression significantly improved PCNA expression, which presents for cancer cells proliferation, and α-SMA and FN1 expression in mesenchyma." (PMID 37723559, 2023). "Quantitative RT–PCR analysis was used to verify that SOX1 controlled the expression of genes related to pathways in cancer, such as LAMB3, FN1, and HES1, and the focal adhesion pathway, including LAMB3 and FN1." (PMID 37190139, 2023). "TGFB2 was included in a four gene signature (FN1, TGFB2, TGFBR2, and TGFBI), as an indicator of CAF abundance, which predicted survival in TCGA pan-cancer cohort comprising 9356 patients from 32 cancer subtypes." (PMID 37296997, 2023). "We therefore evaluated the expression of a panel of epithelial (KRT5, 7, 8, 18, and CDH1), mesenchymal (VIM, FN1, SNAI1, TWIST1, COL1A1, and PRRX1), and cancer stem cell (ALDH1A2, ALDH7A1, CD44, and CCND1) markers in all samples." (PMID 36980717, 2023). "The cancer cell clusters in NBNC-HCC3 cells were recognized as three clumps (clusters #4, #5, and #14) and most of the cells expressed a fibrosis marker Fn1 strongly." (PMID 38201587, 2023). "As EMT is a common process that has been postulated to be responsible for carcinoma cell metastasis, the effect of the BCSC secretome on the expression of epithelial markers (CDH1, TJP1 and OCLN) and mesenchymal markers (Snail, FN1, MMP2 and VIM) was assessed." (PMID 36915147, 2023). "The expression of TF-protein FOXL1 (a regulator of NT5E, TP53INP1, HPGD, FN1, OAS1 and NQO1) is connected with numerous cancer." (PMID 35617355, 2022). "In Cluster 2 the EMT related genes, including Fn1, Vim and Sdc1, were significantly upregulated, suggesting that Cluster 2 underwent active EMT, one of the major features of cancer progression." (PMID 35941362, 2022).
cancer (continued). "Some of these AASEs affect genes that are not only associated with immunity but also play essential roles in inflammation (e.g., FN1 and HYAL2) and cancer oncogenesis (e.g., CTTN, FN1, and DGKZ)." (PMID 35752626, 2022). "In the 178 PC patients, the LAMB3, FN1, KRT17, KRT19, and ANXA1 were also upregulated in cancer tissue, compared with adjacent tissues and normal tissues." (PMID 35428170, 2022). "Decrease expression of FN1 and SOX2 indicating the inhibition of migration, invasion, and maintenance of cancer stem cell stemness." (PMID 36601474, 2022). "As the core genes of m7G score model, FN1 and ITGB1 are highly expressed not only in the stroma and epithelial cells of ADM and PDAC, but also in pan-cancer." (PMID 35979350, 2022). "We used pan-cancer expression data to find 14-LncRNAs that had a high correlation with the EMT markers VIM, CDH1, FN1, SNAI1, and SNAI2." (PMID 36120580, 2022). "FN1, IL10, and MYC activation were related to the poor prognosis, indicating a pivotal role in cancer progression." (PMID 36389789, 2022). "The study identified FN1, CD44, TIMP1, SPARC and SNAI2 as common coding hub proteins for most of the drug-resistant cancer types." (PMID 35534592, 2022). "In contrast, for patients with lower number of NART responses, we observed high expression of FN1, ITGA5 and COL3A1, which is correlated with poor survival for cancer patients." (PMID 35410325, 2022). "Vimentin, MMP9, FN1, and N-Cadherin are the well-known genes that have the main contribution to metastasis and EMT (Epithelial-to-mesenchymal transition) in cancer." (PMID 35193569, 2022). "Many of these DEGs, including CGA, CDKN1A, FN1, CLIC3, and S100P, have been reported to play essential roles in cancer progression." (PMID 35521536, 2022). "From heatmap analyses, it was observed that all of these protein-coding hub genes were up-regulated in the case of Ponatinib-resistant cancer and only FN1, CD44 and TIMP1 were up-regulated in Foretinib-resistant cancer." (PMID 35534592, 2022). "Then, we analyzed the upregulated top five differentially expressed genes between the paracancer tissue and the cancer tissue, which included LAMB3, FN1, KRT17, KRT19, and ANXA1." (PMID 35428170, 2022). "FN1 was previously shown to be able to activate MMP2 and MMP9 expression during malignant tumor progression, facilitating cell migration, invasion, and distant metastasis." (PMID 34758823, 2021). "In addition, analysis of the UALCAN database showed that FN1 expression levels were closely correlated to cancer stage and that the degree of methylation of the FN1 promoter was lower in THCA than that in normal tissues, indicating that FN1 may be involved in the development of THCA." (PMID 35141255, 2021). "The implication of FN1 fibrillogenesis in the availability of growth factors and in particular of TGF-β1, strengthens its contribution in cancer progression, invasion and metastasis." (PMID 33731188, 2021). "PDGFB, FN1, and VEGFA were the common genes involved in the regulation of cell adhesion, response to wounding, and pathways in cancer." (PMID 34606420, 2021). "In conclusion, six core genes including COL3A1, EEF2, FN1, PTPRF SDC2, and RAC1, and several cancer-related metabolic processes, signaling pathways, and overall survival rate of patients were identified in BM PCa." (PMID 34229299, 2021). "As was reported, several hub collagen-related genes including FN1, IL6, COL4A4 and COL7A1 were involved in the progression and development of variable cancers." (PMID 34960256, 2021). "Increased activation of FN1, a key component of the ECM, has been detected in metastasis and aggressiveness such as radio-resistance in various cancers." (PMID 34746236, 2021). "When GSK3β is inhibited by AKT, free β-catenin accumulate and translocate to the nucleus, ultimately activating downstream target genes such as cyclin D1, C-Myc, CD44, FN1, C-JUN, Slug, L1CAM, and MMP14; thus contributing to tumorigenesis and EMT of cancer." (PMID 34546849, 2021).
cancer (continued). "This last group included genes involved in cell migration and ECM (e.g. RAB6B, FN1, VCAM1 or COL14A1) and genes of signalling pathways usually deregulated in cancer, such as Notch and Wnt signalling (JAG1 and WNT7B, respectively)." (PMID 34353313, 2021). "Our histopathological evidence has shown that COL12A1 and FN1 are expressed from stromal cells, THBS2, and VCAN from stromal and cancer cells, while ITGA2, LAMB3, and LAMC2 are expressed solely from the cancer cells." (PMID 34007003, 2021). "The role of FN1 in ECM composition during development, in tissue homeostasis and cancer is mainly attributable to cFN1." (PMID 33731188, 2021). "We therefore analyzed the expression of mRNA for CD117 and the M2 markers IL-10, fibronectin-1 (FN1), and arginase 1 (ARG1) in total leukocytes from cancer patients and HDs." (PMID 34090509, 2021). "Upregulation of both FN1 and CCND1 messenger RNA was related to cancer invasion and mesenchymal phenotype." (PMID 32037399, 2020). "Seven target genes, namely DDX5, SOS2, ACTG1, EZR, FN1, HCLS1 and PIK3R5, were involved in proteoglycans in cancer signaling pathway." (PMID 32293320, 2020). "In our study, we analyzed the Cancer Cell Line Encyclopedia (CCLE), The Cancer Genome Atlas (TCGA), and the Genomics of Drug Sensitivity in Cancer (GDSC) database, to select six genes (FBN1, FN1, HGF, MMP9, THBS1, and VCAN) as target genes." (PMID 33014013, 2020). "Fibronectin 1 (FN1) is a glycoprotein in the ECM, which can mediate the metastasis of various cancers by activating MMP2 and MMP9 expression." (PMID 32943996, 2020). "EPHA4 showed similar expression in AEC and advanced carcinoma, while FN1 showed down-regulation of expression in AEC and up-regulation in advanced carcinoma." (PMID 33322258, 2020). "Cancer-related genes MUC1, FN1, and S100-family members were the most clinically relevant in CPTC, while APLN and IL16, both immune-related, were clinically relevant in FVPTC." (PMID 31443155, 2019). "A mesenchymal signature (VIM, FN1, LOX, GPC6, ZEB1) was defined as the highest co-correlated mesenchymal marker set in Cancer Cell Line Encyclopedia (CCLE) NSCLC cell lines." (PMID 31581742, 2019). "Further investigations of the remaining genes such as FN1, EEF1A1, COL1A1, SFTPB, SFTPC, and ATP1A1 will shed light on the identification of novel biomarker genes for a pan-cancer cohort." (PMID 31324856, 2019). "Therefore, ITGA2 and FN1 may play key roles in PTC progression via these cancer-related pathways." (PMID 30414611, 2018). "In conclusion, our results suggested the important roles of ITGA2, FN1, ICAM1, TIMP1 and CDH2 in the progression of PTC via various cancer-related pathways." (PMID 30414611, 2018). "FN-1 is involved in HCC as it can be upregulated by HBxAg in an NFkB-dependent way, while is generally over-expressed in several cancers [reviewed in Ref." (PMID 29713327, 2018). "We screened for cancer cells expressing at least one EMT marker, such as ACTA2, EPCAM, CD44, THY1, VIM, FN1, ZEB1 or CDH1." (PMID 29079795, 2017). "The AS events significantly altered in all three cancer types include many genes whose splicing was known to play critical roles in cancer development, such as the CD44, NUMB, and FN1." (PMID 25749525, 2015). "Taken together, it is likely that splicing changes in FN1, FBLN2, AP2B1 and TCF20 are also drivers of cancer initiation and progression, which still needs to be determined functionally." (PMID 25908786, 2015). "Some of the other identified targets of miR-200c include Moesin (MSN), Fibronectin 1 (FN1), and Rho GTPase activating protein 19 (ARHGAP19), important regulators of the migratory and invasive capacity of cancer cells." (PMID 26283969, 2015). "When PanIN samples were compared to PDACs, the most commonly up-regulated genes in the cancers were POSTN, COL1A2, SULF1, FN1, IGHM, VCAN and XIST, and these down-regulated were PGC and PPY." (PMID 23372777, 2013).
cancer (continued). "Jun, CSF2 and IL-8 showed increased expression in IMR90 cells, whereas, NFκB1, NFκBIA, FN1 (fibronectin 1), GADD45A, BIRC2, TMEPAI (prostate androgen induced RNA) and CEBPB (CCAAT/enhancer binding protein) were up regulated in cancer cells." (PMID 22321936, 2012). "All the down-regulated genes, in this Panel 3 showed their significant up-regulation in most of many types of cancers (TGM2, CSNK1A1, CTNNA1, NAMPT/Visfatin, TNFRSF1A, ETS1, SRC-1, FN1, APLP2, DMBT1/SAG, AIB1, AZIN1)." (PMID 23122428, 2012). "FN1 functions in cell migration through integrin binding and can activate focal adhesion kinase (FAK) leading to increased motility and invasion of carcinoma cells." (PMID 21501518, 2011). "Most of the candidate genes of which we confirmed cancer-specific AS in NSCLC are also involved in these processes (ADD3, CLSTN1, FN1, MYO18A, NUMB, SYNE2, and TPM1)." (PMID 21118496, 2010). "From a clinical point of view, IL1RN, MAL and TGM3 were not clearly identified as potential HNSCC markers, while few data have been published concerning the implication of FN1, KRT, MMP1, PLAU and SPARC in this type of cancer." (PMID 19835631, 2009). "Epithelial Mesenchymal Transition (EMT) was another pathway depleted upon knockout, and subsequent analysis revealed a significant correlation between NNMT and EMT-related genes (VIM, CDH2, FN1, TGFB1, and ZEB2) in both the Cancer Cell Line Encyclopedia (CCLE) panel and patient data." (PMID 41997904, 2026). "Furthermore, SERPINE1 interacts with various proteins such as TGFB1, FN1, MMP1, influencing cancer cell adhesion, and motility." (PMID 39817507, 2025). "FN1 can drive the occurrence and progression of various cancers through metabolic reprogramming, while the overexpression of S100A2 can enhance glycolysis and promote cancer cell proliferation." (PMID 41176774, 2025). "However, our study shows a significant downregulation of FN1 in UCEC, indicating a complex and potentially context-dependent role of FN1 in cancer progression." (PMID 39833941, 2025). "In conclusion, STA may exert its therapeutic effect on cancer by regulating JAK-STAT signaling pathway and FN1." (PMID 40772037, 2025). "Incoming signals from cancer cells to PIAS1+ CAFs were subtly altered, including integrin and laminin-mediated adhesion pathways (e.g., FN1–ITGAV_ITGB1, FN1–ITGA5_ITGB1, LAMB3–CD44 and LAMC2–CD44), which support basement membrane integrity rather than invasion." (PMID 40941002, 2025). "Similarly, several effector molecules, including CALD1, CDH1, FN1, FZD7, RAC1, STAT3, and WNT11, were downregulated in cancer cells treated with DBMSCs." (PMID 39768220, 2024). "Moreover, in shared signaling communication networks involving both cell types (e.g., COLLAGEN, LAMININ, FN1, MK, and THBS), the contribution of high PAK2-expressing cancer cells was markedly greater than that of low PAK2-expressing cancer cells." (PMID 38343537, 2024). "UBE2M, FN1, and RECQL4, for example, fell among our top 12 common-cancer seed hubs." (PMID 39657701, 2024). "The treatment of cancer cells with DBMSCs in the IC setting modulated the expression of various factors with a specific role in cellular adhesion, including AKT1, CALD1, CDH1, FN1, and STAT3." (PMID 39768220, 2024). "Furthermore, FN1 has been shown to control cell survival, proliferation, and epithelial–mesenchymal transition (EMT) in cancers." (PMID 39770638, 2024). "Both COL1 and FN1 have been detected in solid ovarian metastases but not in ascites cells, and it was thought that they originate from stromal cells rather than cancer cells." (PMID 38264656, 2023). "Outgoing signaling patterns upregulated in LE-LE signaling, relative to TC-TC signaling, included Collagen, Laminin, Tenascin, FN1, MIF, APP, CD99, Notch, and CSPG4 pathways, reinforcing the role of these pathways in facilitating cancer invasion and metastasis." (PMID 37596273, 2023).